BCL2 (BCL2 apoptosis regulator)
Diseases named in the same sentence as BCL2 in open-access papers (continued):
Sharing a sentence is not in itself a finding about the gene and the disease.
intracranial hypertension (2 papers, 2020 to 2024). A finding characterized by increased cerebrospinal fluid pressure within the skull. "Intracranial hypertension caused increased abundance of Bax and cleaved caspase 3, accompanied with decreased protein expression of Bcl‐2, both of which were partially diminished by Piezo1 inhibitor GsMTx4." (PMID 39328029, 2024). "Possible mechanisms may be increased risk of intracranial hypertension and development of cerebral edema as a result of apoptosis activation due to variable levels of Bcl-2 protein expression." (PMID 32570722, 2020). "In our in vitro study, apoptosis‐associated protein Bax and cleaved caspase 3 were significantly increased and Bcl‐2 was decreased when primary neurons subjected to 12 kpa intracranial hypertension environment." (PMID 39328029, 2024). "Piezo1 knockdown attenuated intracranial hypertension‐induced increased protein of Bax and cleaved caspase 3, and reversed protein level of Bcl‐2 to control levels." (PMID 39328029, 2024).
juvenile dermatomyositis (2 papers, 2006 to 2024). Juvenile dermatomyositis (JDM) is the early-onset form of dermatomyositis (DM), a systemic, autoimmune inflammatory muscle disorder, characterized by proximal muscle weakness, evocative skin lesion, and systemic manifestations. "Thirty-six patients with jSLE, 13 juvenile dermatomyositis (JDM) inflammatory controls, and nine healthy controls had Fas, FasL, TRAIL, TNFR1, Bcl-2, Bax, Bim, and caspase-3 expressions in NK cells (CD3−CD16+CD56+) simultaneously determined by flow cytometry." (PMID 38562920, 2024). "The aims of this study were to determine the expression of Fas antigen and Bcl-2 protein on peripheral blood T and B lymphocytes from patients with juvenile-onset systemic lupus erythematosus (JSLE), juvenile rheumatoid arthritis (JRA) and juvenile dermatomyositis (JDM)." (PMID 17162369, 2006).
knee osteoarthritis (2 papers, 2021 to 2025). "In addition, warm acupuncture combined with BMSCs treatment suppressed chondrocyte apoptosis in rabbits with knee osteoarthritis by reduced TUNEL-positive chondrocytes and simultaneously reversed the mRNA expression of Bax, Bcl-2, and Caspase-3." (PMID 34422071, 2021).
Leber congenital amaurosis (2 papers, 2013 to 2016). Leber congenital amaurosis (LCA) is a retinal dystrophy defined by blindness and responses to electrophysiological stimulation (Ganzfeld electroretinogram (ERG)) below threshold, associated with severe visual impairment within the first year of life. "We previously reported that the altered regulation of α-crystallins was correlated with triggering of the Bcl-2-apoptotic pathway during progression of the disease in the Rpe65−/− mouse model of Leber's congenital amaurosis (LCA), an autosomal recessive form of retinitis pigmentosa (RP)." (PMID 23383327, 2013). "Immunohistochemical assays of the epithelial membrane antigen (EMA), S100, vimentin, KI67, creatine kinase (CK), Leber congenital amaurosis (LCA), CD68, antibodies against glial fibrillary acidic protein (GFAP), BCL2, anaplastic lymphoma kinase (ALK), and synaptophysin levels were performed." (PMID 27917338, 2016).
lenti-virus infection (2 papers, 2011 to 2025). "We constructed stable Bcl-2 knockdown cells (BC3-shBcl2, BJAB-shBcl2) and their control cells (BC3-shC,B JAB-shC) by lentivirus infection and puromycin selection." (PMID 21901143, 2011).
leukopenia (2 papers, 2020 to 2024). "The first clinical trials with the dual BCL-2/BCL-XL inhibitor ABT-263 revealed that the dose-limiting side effects are leukopenia and thrombocytopenia." (PMID 33070156, 2020). "Through molecular docking analysis, it was discovered that QJSB has a significant impact on the expression of apoptotic proteins BAX, BCL2, CASPASE3, and CYTC in mice with leukopenia." (PMID 39295929, 2024). "Notably, AKT1, EGFR, IL6, STAT3, BCL2, CASP3, and JUN were identified as the top seven targets (degree >80) and may be key targets of QJSB in treating leukopenia." (PMID 39295929, 2024).
lichen planus (2 papers, 2012 to 2013). A chronic, recurrent, pruritic inflammatory disorder of unknown etiology that affects the skin and mucus membranes. "In summary, both lichen planus and OSCC show similar expressions for p-53 and bcl-2, and it is possible that alterations of these genes may be relevant in the long term transformation process of OLP to OSCC." (PMID 22549684, 2012). "In those cases of lichen planus in which Bcl-2 was absent, Bax may have bound with other regulatory proteins, including other members of the Bcl-2–related family, such as Bcl-x, McL-1, Bad or Bak." (PMID 24551804, 2013).
lobular carcinoma (2 papers, 2002 to 2025). "Invasive lobular carcinoma is excluded on the basis of the focal and weak positivity for CK7, strong positivity for BCL-2 and negativity for ER and PR." (PMID 40345046, 2025).
lymphoblastic lymphoma (2 papers, 2014 to 2021). A lymphoma composed of immature small to medium-sized precursor lymphoid cells (lymphoblasts). "As the results of a preclinical study suggested that ALL cells were dependent on both BCL-2 and BCL-XL, navitoclax (a BCL-2 and BCL-XL inhibitor) was tested in combination with venetoclax and chemotherapy for pediatric and adult patients with relapsed/refractory ALL or lymphoblastic lymphoma." (PMID 33946897, 2021).
Merkel Cell Carcinoma (2 papers, 2020 to 2022). "BCL-2 in Merkel cell carcinoma (MCC) patients indicates an earlier clinical stage and longer survival in patients." (PMID 36569952, 2022).
mesenchymal neoplasms (2 papers, 2023 to 2025). "The diffuse expression of CD45, CD33, CD43, and BCL-2 in our case was instrumental in confirming the myeloid origin and ruling out other hematolymphoid or mesenchymal neoplasms." (PMID 41234969, 2025). "In addition, several mesenchymal tumors have been reported to express both CD99 and bcl-2." (PMID 37315497, 2023).
migraine (2 papers, 2023 to 2025). "Furthermore, the PI3K-Akt signaling pathway is an important survival signal transduction pathway in cells; when activated in the brain tissue of a rat migraine model, it involves seven targets, including Akt1, IL-6, and BCL2." (PMID 41009787, 2025). "As Bax, Bcl-2 and ROS are closely related to cell apoptosis, the abnormal Bax, Bcl-2 and ROS levels in study suggest that migraine may also be related to neurocyte apoptosis." (PMID 37123270, 2023). "Moreover, molecular docking results demonstrated that these core components have a strong affinity with multiple target proteins such as PTGS2, PPARG, BCL2, CASP3, TNF, and ESR1, suggesting that ginkgo seeds exert their therapeutic effects on migraines through multiple targets and pathways." (PMID 41009787, 2025).
mucinous adenocarcinoma (2 papers, 2019 to 2025). An invasive adenocarcinoma composed of malignant glandular cells which contain intracytoplasmic mucin. "Some studies have demonstrated Bcl-2 positivity in more than 30% of a mucinous adenocarcinoma." (PMID 31754362, 2019).
mucinous tumors (2 papers, 1998 to 2012). "In the same study, they have showed that although there was not difference in mucinous tumors, serous tumors have significant difference in bcl-2 positive staining." (PMID 22995373, 2012).
myxofibrosarcoma (2 papers, 2023). A malignant fibroblastic neoplasm arising from the soft tissue. "The pro-apoptotic markers Bak and Bim exhibited increased expression in myxofibrosarcoma cells, while the anti-apoptotic Bcl-2 showed a significantly notable decrease in expression." (PMID 37958891, 2023). "In terms of immunohistochemistry, low-grade myxofibrosarcoma was positive for MUC4, BCL-2, CD99, and vimentin." (PMID 37189471, 2023).
neuro degenerative diseases (2 papers, 2020 to 2023). "In research for HD, as well as a progressive neurodegenerative disorder, the researchers described that ZNF148 directly interacted with three known-HD genes (BCL2, CASP6, and IRS2)." (PMID 37360784, 2023).
neuropathies (2 papers, 2021 to 2023). "The results of the H&E staining, Nissl staining, and Bcl-2 protein expression showed that the neuronal cells in the hippocampus of the T2DM neuropathy rats had undergone harmful changes, including loss, degeneration, and apoptosis." (PMID 37165590, 2023). "Furthermore, the immunostaining results revealed that in the T2DM neuropathy rats, the expression of FIB, GFAP, and IBA1 was upregulated, and the expression of CD31 and Bcl-2 was downregulated." (PMID 37165590, 2023).
nevus (2 papers, 2018 to 2025). Nevus (or naevus, plural nevi or naevi, from nævus, Latin for "birthmark") is the medical term for sharply circumscribed[1] and chronic lesions of the skin or mucosa. "Using an NrasQ61K-transgenic GCMN mouse model, which mimics the common mutation in Chinese GCMN patients, we demonstrated that venetoclax, a BCL2 inhibitor, effectively induces hypopigmentation and clears nevus cells via intralesional injection or oral administration." (PMID 40374605, 2025).
Non-alcoholic fatty liver disease (2 papers, 2021 to 2023). "In addition, a recent study has investigated the role of VitD in non-alcoholic fatty liver disease in rats and reported a similar result found in our study: VitD injection enhances the expression of Bcl2 compared to the group fed only with an HFD." (PMID 36661517, 2023). "Non-alcoholic fatty liver disease (NAFLD) and non-alcoholic steatohepatitis (NASH) are both characterized by liver injury and inflammation, which are driven in part by excessive apoptosis of hepatocytes due to low BCL2 expression." (PMID 33513764, 2021).
ocular hypertension (2 papers, 2018 to 2023). Abnormally high intraocular pressure. "Based on these findings, AA protects RGCs from ocular hypertension by upregulating the expression of the antiapoptotic marker Bcl-2 and downregulating the expression of the pro-apoptotic markers Bax and caspase-3." (PMID 30079010, 2018).
oculopharyngeal muscular dystrophy (2 papers, 2015). Oculopharyngeal muscular dystrophy (OPMD) is an adult-onset progressive myopathy characterized by progressive eyelid ptosis, dysphagia, dysarthria and proximal limb weakness. "Forced-expression of Bcl2 was observed to ameliorate the loss of grip strength in a mouse model of oculopharyngeal muscular dystrophy." (PMID 26557094, 2015).
oral epithelial dysplasia (2 papers, 2022 to 2024). "The present study aimed to examine the KRAS expression in oral epithelial dysplasia and squamous cell carcinoma of the oral cavity and to correlate its expression with the established prognostic markers (Ki-67, bcl2, and Cyclin D1) and the available clinicopathologic factors." (PMID 36532636, 2022). "The paraffin-embedded tissue was analyzed for the expression of KRAS for oral epithelial dysplasia and OSCC, and ki-67, Cyclin D1, and bcl2 were analyzed only for OSCC." (PMID 36532636, 2022).
Ovarian cyst (2 papers, 2021 to 2023). The presence of one or more cysts of the ovary. "On the other side, the expression of Bcl-2 was significantlyelevated in these patients indicating a low rate of apoptosis in their ovarian cysts.Likewise, Isobe and Yoshimura showed that the expressions of caspase-3 and BAX wassignificantly reduced in bovine cystic ovarian disease." (PMID 33687162, 2021).
pancreatic adenocarcinoma (2 papers, 2011 to 2018). "Anti-apoptotic proteins like BCL-2 may be induced by activated STAT3, and in pancreatic adenocarcinoma cells, the combination of JQ1 and SAHA diminished STAT3 phosphorylation to downregulate BCL-2." (PMID 29312470, 2018).
pancreatic NETs (2 papers, 2023 to 2024). "Currently, there are no data on the role of Bcl-2 inhibitors in pancreatic neuroendocrine tumors." (PMID 37620408, 2023).
parathyroid adenoma (2 papers, 2002 to 2006). "One study revealed that 76% of the patients with typical parathyroid adenoma had a phenotype of p27(+)bcl-2(-)Ki-67(-)mdm2(+) compared to none of those patients diagnosed with PC." (PMID 16504029, 2006).
parotid gland (2 papers, 2009 to 2012). "The present study aims to investigate the immunohistochemical expression of murine double minute-2 (mdm-2), p27Kip1 and B cell lymphoma-2 (bcl-2) in Warthin's tumor of parotid gland and also to clarify the role of these proteins in the behavior of that tumor." (PMID 19445705, 2009).
peritoneal carcinoma (2 papers, 2000 to 2021). A peritoneum cancer that is located in the inside of the abdomen.
pilomatricoma (2 papers, 2021 to 2025). "Immunohistochemical staining was performed on the pilomatricoma tissue, using beta-catenin and bcl2 monoclonal antibodies." (PMID 34956371, 2021). "The other researchers discovered the bcl-2 oncogene overexpression in pilomatricoma basophilic cells." (PMID 34956371, 2021). "In addition to beta-catenin, the expression of bcl2 was observed in pilomatricoma." (PMID 34956371, 2021). "No beta-catenin nor bcl2 proteinn expression was observed on the basaloid cell or transitional cell components of the pilomatricoma by immunohistochemical analysis." (PMID 34956371, 2021). "In this study, we found that beta-catenin and bcl-2 protein were not expressed in the pilomatricoma tissue obtained from our patient." (PMID 34956371, 2021).
pituitary cancer (2 papers, 2017 to 2020). A primary or metastatic malignant neoplasm affecting the pituitary gland. "Besides, it was uncovered that gossypol induces apoptosis and upregulates miR-15a, a BCL-2-targeting miRNA, in pituitary cancer cells, suggesting that gossypol can also indirectly limit BCL-2 activity." (PMID 33066509, 2020).
Pleural effusion (2 papers, 2018 to 2020). The presence of an excessive amount of fluid in the pleural cavity. "FISH of original FL cells from patient's pleural effusion showed 65% cells had IGH(14q32)/BCL2(18q21) and 64% cells had BCL2 (18q21) gene rearrangement." (PMID 32459397, 2020).
pneumococcal meningitis (2 papers, 2009 to 2016). An acute purulent infection of the meninges and subarachnoid space caused by Streptococcus pneumoniae, most prevalent in children and adults over the age of 60. "We here show that transgenic expression of Bcl-2 in haematopoietic cells blocks the resolution of inflammation following antibiotic therapy in a mouse model of pneumococcal meningitis." (PMID 19478887, 2009).
Polycythemia vera (2 papers, 2011 to 2012). "Moreover, it has been previously demonstrated that transcription of the anti-apoptotic Bcl-2 protein is regulated by the STAT3/5 signaling pathway and that Bcl-2 is overexpressed in erythroid cells from patients with polycythemia vera." (PMID 22418850, 2012).
polyp (2 papers, 2014 to 2024). A usually exophytic mass attached to the underlying tissue by a broad base or a thin stalk. "Regarding gene expression characteristics in polyp tissues, some studies showed that postmenopausal bleeding EP patients exhibited higher estrogen receptor, progesterone receptor, KI67, and BCL2 levels in the polyp epithelium and stroma compared to the adjacent endometrium." (PMID 38473810, 2024).
postmenopausal osteoporosis (2 papers, 2019 to 2025). Metabolic disorder associated with fractures of the femoral neck, vertebrae, and distal forearm. "Later, we conducted in vitro cell experiments based on the mouse model of postmenopausal osteoporosis to further improve the effect of casticin on osteoclast generation in animals through NF-κB/BCL-2 signaling pathway." (PMID 39947684, 2025). "Notably, in specific osteoporotic conditions like postmenopausal osteoporosis, abnormally high BCL-2 expression coincided with the abnormal activation of the NF-κB signaling pathway." (PMID 39947684, 2025). "In addition to Bcl-xl and Bim, Bcl-2 plays roles in osteoclast apoptosis and pathology of postmenopausal osteoporosis." (PMID 31546863, 2019).
prediabetes (2 papers, 2022 to 2025). "miR-27 was up-regulated in obese prediabetes, targeting regulators of oxidative stress and apoptosis such as BCL2, BMI1, FOXO3, and suppressing SIRT1, thereby amplifying IL-6 production." (PMID 41400625, 2025). "Through real-time quantitative PCR analysis, we found that the mRNA level of Bax and Caspase-3 were increased, whereas the level of Bcl-2 was decreased in prediabetes-FMT group." (PMID 35606800, 2022). "Western blot results also confirmed that the relative protein level of both actived-CASPASE3/pro-CASPASE3 and BAX/BCL-2 increased in prediabetes-FMT group, while the rescue-FMT group showed a protective effect." (PMID 35606800, 2022). "Through immunohistochemical staining, we found that the expression of apoptotic path-related BAX protein and CASPASE-3 protein were increased in prediabetes testes and epididymis, whereas the expression of BCL-2 was decreased in prediabetic testes." (PMID 35606800, 2022).
primary biliary cholangitis (2 papers, 2016 to 2022). Primary biliary cholangitis (PBC) is a chronic and slowly progressive cholestatic liver disease of autoimmune etiology characterized by injury of the intrahepatic bile ducts that may eventually lead to liver failure. "In addition, biliary epithelial cells are Bcl2 positive in primary biliary cirrhosis (PBC), an inflammatory condition of bile ducts that leads to fibrosis and cirrhosis." (PMID 26838806, 2016).
primary cutaneous lymphoma (2 papers, 2009 to 2023). Cutaneous lymphoma is a heterogeneous entity with respect to its clinical and pathological features, evolutive profile, prognosis, molecular etiology and response to therapy. "Primary cutaneous diffuse large B-cell lymphoma, leg type (PCDLBCL-LT), is a rare and aggressive variant of primary cutaneous lymphoma that typically expresses B cells as well as MUM1/IRF4, BCL2, and FOXP1, whereas BCL6 may be present or undetectable." (PMID 37754668, 2023).
primary sclerosing cholangitis (2 papers, 2020 to 2021). "We observed increased cellular apoptosis, as revealed by the TUNEL assay and the expression of the apoptotic markers Bcl2 and Bax in the early stage of DDC-induced sclerosing cholangitis, which was reversed after the recovery phase." (PMID 34209524, 2021).
Pruritus (2 papers, 2019 to 2024). Pruritus is an itch or a sensation that makes a person want to scratch. "In our cohort, the BCL2/BAX ratio resulted associated both with the presence of pruritus 1 month after the completion of RT treatment, and with the class of patients classified as radiosensitive by means of IRS index." (PMID 31632918, 2019). "Symptoms of pruritus resulted associated at t1 with a 0.79-fold change of XPC and with a 1.01-fold change of ZMAT3; at t2 pruritus was associated with a 0.87-fold change of ATM, and a lower BCL2/BAX ratio (respectively, 0.76- vs. 1.15-fold change)." (PMID 31632918, 2019). "Clearly, some genes such as AKT1, ALB, BCL2, STAT3, JUN, ESR1, and TNF hold important positions within the network, indicating their strong relevance to the pathogenesis of pruritus and their potential as key targets for drug intervention." (PMID 39606625, 2024).